APC (APC regulator of Wnt signaling pathway)
Diseases named in the same sentence as APC in open-access papers (continued):
Sharing a sentence is not in itself a finding about the gene and the disease.
cancer (continued). "Another oncogenic Cdc20 subunit in the APC/C complex may be a therapeutic target for cancer treatment." (PMID 37341064, 2023). "In SW480 CRC cells, which have constitutively activated Wnt due to mutation of APC, EHT inhibited the size of cell spheroids in hanging drop cultures and, importantly, significantly inhibited macropinocytosis uptake of TMR-dextran in these cancer cells." (PMID 37902809, 2023). "Interestingly, cogent new evidence suggests that upstream Wnt receptor nanoclustering is required for cancer development on a mutant APC background in Drosophila and mammalian cells, further supporting the non-autonomous nature of mutant APC in CRC10,13." (PMID 37468468, 2023). "In addition, CTNNA1 can promote the metabolism of β-catenin by stabilizing APC, thereby inhibiting the Wnt pathway and suppressing cancer development." (PMID 36741258, 2023). "The APC-WNT signaling pathway also affects cancer metabolism." (PMID 36879264, 2023). "Moreover, recently K-ras mutation was demonstrated to activate cancer stem cells, contributing to colorectal tumorigenesis and metastasis in CRC cells harboring APC mutations." (PMID 37098074, 2023). "Therefore, when CDH1 is depleted, increased PFKFB3 causes an upregulation of glycolysis and cell proliferation, suggesting that APC/CCDH1 modulation is important in cancer metabolism alteration." (PMID 37176148, 2023). "Moreover, APC is highly specifically expressed in brain tissues and bipolar cells but has low expression in most cancers." (PMID 35303016, 2022). "However, the present evidence based on clinical results cannot sustain the effect of APC activity in different cancers." (PMID 35303016, 2022). "However, APC can be expressed in all tissues, with low RNA tissue specificity and is expressed in nearly all cancer cells." (PMID 35303016, 2022). "The risk for developing cancers, other than CRC, in AJ APC I1307K carriers was previously reported." (PMID 36497357, 2022). "It was interesting to investigate novel interactions of APC with nuclear transcription factors which could expand on the functional importance and role of APC in cancer." (PMID 36457029, 2022).
cancer (continued). "In contrast, there were also APC variant carriers without a history of GI cancer, although some dogs showed GI symptoms suggestive of cancer development." (PMID 35717217, 2022). "The APC gene, a Myc suppressor gene, has been reported to be mutated in 20–50% of patients with cancer and in approximately 30% of AD in non-polyposis patients." (PMID 35050180, 2022). "Further research showed that growth factors, cancer-associated mutations (KRAS, mutated APC), or cancer-related transcription factors (cMYC) could up-regulate HMGA1 in specific contexts." (PMID 35805937, 2022). "A similar principle could serve as an explanation for increased mitochondrial vulnerability of Wnt‐low cancer cells upon APC truncation." (PMID 35904277, 2022). "Additionally, we calculated the frequencies of genes in the three phenotypes, which were reported to be associated with the invasion and progression of cancer, such as SMAD4, APC, and ERBB4." (PMID 35401671, 2022). "In addition, the analysis of the TCGA database showed that the APC gene has low cancer specificity and cell type specificity, but it is enhanced in neuronal cells, especially bipolar cells." (PMID 35303016, 2022). "For instance, alterations in the CTNNB1 and APC genes can lead to activation of the Wnt signaling pathway, whereas activating GNAQ mutations can lead to Hippo-independent activation of YAP pathways and cancer progression." (PMID 36497457, 2022). "However, GSK3B (Glycogen Synthase Kinase 3 Beta) acts as a negative regulator in the phosphorylation of key cancer-related genes, such as APC, JUN, and CTNNB1/beta-catenin." (PMID 35645340, 2022). "Different anti-cancer treatments have been shown to target APC to inhibit glycolysis in CRC cells." (PMID 34571724, 2021). "In contrary to APC, BRAF mutation is associated with high cancer immunity." (PMID 34211853, 2021). "The APC-Asef interaction plays a vital role in cancer invasion and metastasis." (PMID 33670371, 2021). "Indeed, deleterious CNVs in cancer patients have been observed in more than 30% of highly penetrant cancer-predisposing genes, including BRCA1, BRCA2, APC, as well as mismatch repair (MMR) genes." (PMID 33503040, 2021). "Comparing the mutation status of cancer critical genes in PUMC-CRC1 with that in 19 commonly-used CRC cell lines, PUMC-CRC1 was a unique cell line with APC (p.T1493fs), KRAS (p.G12V) and SMAD4 (p.V506A) mutations, which enriches the diversity of CRC cell lines." (PMID 34162944, 2021). "Sporadic cases of cancers, on the other hand, didn’t show alterations in the APC gene." (PMID 34552611, 2021). "To confirm cancer-cell content in our low-volume primary tissue specimen, we have developed a multiplex epigenetic biomarker assay to detect promoter methylation of PC-associated genes including GSTP1, RASSF1, RARb and APC." (PMID 34581895, 2021). "Regarding those genes involved in germline predisposition to other cancers, ATM, APC, POLD1 or SDHC could be promising candidate genes for germline GC predisposition." (PMID 33525650, 2021). "We demonstrated that YTHDF bound METTL3-mediated m6A of APC mRNA and reduced APC expression, revealing a previously unknown mechanism by which the Wnt/β-catenin pathway is upregulated in cancer in an epitranscriptomal regulation-dependent manner." (PMID 34155197, 2021).
cancer (continued). "Mutations in the WNT (e.g. APC or CTNNB), EGFR (e.g. KRAS, PIK3C or BRAF) and TGF-β (e.g. SMAD4) signalling pathways gradually render cells independent from niche signals to grow autonomously and promoting cancer." (PMID 33594337, 2021). "Beside a well-documented pro-angiogenic effect, PGE2 promotes apoptosis and stimulates growth of tumour stem cells both through the EP2 and EP3 receptors by synergizing with the Wnt/β-catenin pathway, relevant in cancers where the adenomatous polyposis coli (APC) gene is activated." (PMID 34544470, 2021). "MYC, CDKN2A, PTEN, HARS, APC2, and APC are often referred to as miRNAs in cancer." (PMID 33959508, 2021). "As mutation appeared to be more common in cancer tissue, subsequent studies also measured the hypermethylation rate in APC promoter with or without mutation and found that hypermethylation was present in 20 of 108 (18%) tumors lacking APC mutation." (PMID 33968756, 2021). "Analysis of the correlation between CCO immuno-genotype and TIM phenotype revealed that the TIM phenotype was associated with microsatellite instability, Wnt/β-catenin signaling, APC/KRAS mutations, and the unfolded protein response pathway linked to the FBXW7 mutation in cancer cells." (PMID 34256801, 2021). "Mutant APC may also impair cytoskeleton adhesion and stability, which play a role in cancer progression." (PMID 33237662, 2021). "Cellular stress might also stimulate APC protein production retaining some functions in N-terminus and lead to cancer progression." (PMID 34885156, 2021). "It is unclear how FOXJ1 could control the abundance of mutant APC, and it should be noted that FOXJ1 is more commonly associated with cancers in which APC mutations are infrequent." (PMID 34298659, 2021). "Interestingly, APC/CCdh1 is known to behave as both tumor suppressor and oncoprotein in various cancer types." (PMID 33260674, 2020). "Unlike other human cancers, mutations on Wnt components such as APC, Axin, and CTNNB1 (encoding β-catenin) are very rare." (PMID 33126517, 2020). "It is possible that APC mutations, in the context of BRAF mutation, facilitate an exit to oncogene induced senescence and while simultaneously satisfying the requirement for WNT signaling, facilitating a rapid transition to dysplasia and invasive cancer." (PMID 32384699, 2020). "APC was mutated in 82% of these cancers, in comparison to just 28% of BRAF mutant cancers." (PMID 32384699, 2020). "Although this study does not focus on cancer end points, we have shown that inactivation of the adenomatous polyposis Coli (APC) predisposes to epigenetic silencing of FXR in the colon in previous studies." (PMID 33105708, 2020). "SIGLEC family genes were further associated with specific oncogene mutation in different cancer types and were differentially expressed between patients of mutation and non-mutation groups, such as APC in COAD and READ, or CTNNB1 in LIHC." (PMID 33240817, 2020).
cancer (continued). "Analysis of affected individuals belonging to high‐risk pedigrees has long been a powerful design for identification of rare cancer predisposition genes and variants in Utah (e.g., BRCA1 [OMIM 113705], BRCA2 [OMIM 600185], CDKN2A [OMIM 600160], GOLM1 [OMIM 606804], APC, PTEN [OMIM 601728])." (PMID 33118316, 2020). "Whether abnormal accumulation of borealin and/or Aurora B due to defects in APC/CCdh1 regulation contributes to cancer etiology requires further studies." (PMID 32934012, 2020). "Given that DNA-PKcs inhibitors are currently in clinical trials, determining precisely how DNA-PKcs regulates APC/C-mediated degradation of mitotic proteins could have relevance to cancer therapy." (PMID 32284347, 2020). "This makes APC a viable therapeutic target in these cancer types." (PMID 33105836, 2020). "These roles of APC in different DNA repair pathways can not only promote tumorigenesis by increasing the genomic instability, but also have implications for DNA damaging anti-cancer agents." (PMID 33105836, 2020). "Next, we discuss how APC is deregulated for Wnt signaling hyperactivation in cancer cells." (PMID 32037398, 2020). "While APC’s role in contributing to cancer development is well-established, more recent data have shown that the APC status may also influence cancer treatment." (PMID 33105836, 2020). "APC is a component of the destruction complex which promotes ubiquitination of β-catenin and APC functions as a negative regulator of the Wnt signaling pathway and cancer." (PMID 32486158, 2020). "This may explain why precancerous lesions with both APC mutation and BRAF mutation are rarely identified, and why the cancers with these mutations present at a younger age." (PMID 32384699, 2020). "Thus, deregulation of Wnt signaling activity and targeting APC gene can be a novel approach for treatment of cancers." (PMID 32425780, 2020). "However, these CRC cells also contain mutations in other cancer related genes (HCT116: KRAS, PIK3CA, CTNNB1, BRCA2, CDKN2A etc.; SW480 or SW620: KRAS and APC etc.), which constitute a unique pathological context in every CRC cell." (PMID 32388500, 2020). "Through APC’s interactions with DNA repair proteins, DNA replication proteins, tubulin, and other components, recent evidence has shown that APC regulates the chemotherapy response in cancer cells." (PMID 33105836, 2020). "The mechanisms associated with APC mutation induced aggressiveness in the context of BRAF mutant cancers are not clear." (PMID 32384699, 2020). "Additionally, utilizing the mutant adenomatous polyposis coli (APC) gene mouse model of colonic polyps and cancer, mice overexpressing GDF15 are protected from the development of polyps and cancer." (PMID 32502202, 2020). "HDAC2 is reported to be responsible for the loss of adenomatous polyposis coli (APC) expression in colorectal cancer (CRC) and displays increased expression in cervical and gastric carcinomas." (PMID 32582706, 2020). "Moreover, the role of missense APC mutations, which are relatively frequent in serrated lesions and BRAF mutant cancers with MSI, should be further investigated in the serrated pathway." (PMID 31330830, 2019). "Thus, constructing a model that carries both APC and KRAS mutations is also important for thorough molecular evaluation of the cancer." (PMID 31766149, 2019). "Whether circ-APC is also an anti-cancer gene in other types of malignant tumors is worthy of further study." (PMID 31631067, 2019).